SNAP25 (synaptosome associated protein 25)
Diseases named in the same sentence as SNAP25 in open-access papers (continued):
Sharing a sentence is not in itself a finding about the gene and the disease.
ischemia (4 papers, 2013 to 2024). A hypoperfusion of the BLOOD through an organ or tissue caused by a PATHOLOGIC CONSTRICTION or obstruction of its BLOOD VESSELS, or an absence of BLOOD CIRCULATION. "MiR-210-5p was increased in the hippocampus of rats exposed to 4 weeks of ischemia and binds complementarily to synaptosomal-associated protein of 25 KDa (Snap25) mRNA, causing cognitive deficits and synaptic loss, suggesting a potential new therapeutic avenue for the treatment of VD." (PMID 38892378, 2024). "Transient forebrain ischemia reduced PSD95, synaptophysin, and SNAP-25 levels in the hippocampus 1 day and 4 days after ischemia." (PMID 33572372, 2021). "In the Tat-SH3GL2-treated group, however, PSD95, synaptophysin, and SNAP-25 levels were significantly higher in the hippocampus at 1 day and 4 days after ischemia compared to those in the Tat peptide or Control-SH3GL2-treated groups." (PMID 33572372, 2021). "In the Tat peptide- and Control-SH3GL2-treated groups, PSD95 protein levels gradually decreased 1 day and 4 days after ischemia, while synaptophysin and SNAP-25 levels increased 4 days after ischemia." (PMID 33572372, 2021). "PSD95, synaptophysin, and SNAP-25 levels were assessed in the hippocampus by Western blot analysis because ischemia and Tat-SH3GL2 have been shown to affect synaptic plasticity in the hippocampus." (PMID 33572372, 2021). "Despite the fact that synaptosomal-associated protein SNAP-25 has not been detected in astrocytes but SNAP-23, our data revealed mRNA levels coding SNAP-25 were significantly increased in cortical astrocytes 14 days post-ischemia (B3 subpopulation)." (PMID 23940528, 2013).
medulloblastoma (4 papers, 2020 to 2021). A malignant, invasive embryonal neoplasm arising from the cerebellum. "On the other hand, a low expression level of SNAP-25 has been found in medulloblastoma tumors associated with defects in dendrite formation and in the impairment of targeted chemotherapy." (PMID 32545553, 2020). "The results showed lower expression of SYN1 and SNAP25 in the medulloblastoma subtypes compared to normal cerebellum." (PMID 32720471, 2020). "Furthermore, SNAP25 was found to have significantly lower expression levels in medulloblastoma and SNAP25 was crucial for dendrite formation which is associated with the effects of targeted chemotherapy." (PMID 34490096, 2021).
melanoma (4 papers, 2019 to 2025). A malignant, usually aggressive tumor composed of atypical, neoplastic melanocytes. "Besides, researches indicate that SNAP-25 expression increases in the dorsal root ganglia (DRG) of melanoma mouse model, or chronic sciatic nerve pain rats’ model, during tumor-induced pain or nerve injury- induced pain." (PMID 41194174, 2025). "Since melanoma cells show a neuronal phenotype it could be concluded that SNAP25 is important for neuronal-like vesicle generation." (PMID 30823658, 2019). "Contradictorily, SNAP25 was identified to inhibit cancer progression as cleavage of SNAP25 could ameliorate cancer pain of a mouse melanoma model and a comprehensive bioinformatic analysis of GBM indicated that SNAP25 might act as a GBM suppressor and a biomarker in GBM treatment." (PMID 34490096, 2021).
Brain atrophy (3 papers, 2019 to 2024). Partial or complete wasting (loss) of brain tissue that was once present. "In the present study, we demonstrated that GAP43, neurogranin, SNAP25, and synaptotagmin 1 were significantly changed in both EVs and CSF in patients with AD, and these changes corresponded to the severity of brain atrophy." (PMID 38528511, 2024). "The results showed that GAP43, SNAP25, neurogranin, and synaptotagmin 1 were decreased in neuronal-derived EVs but increased in CSF in patients with AD, and the changes corresponded to the severity of brain atrophy." (PMID 38528511, 2024). "Thus, a possible hypothesis for the increased concentrations of synaptic proteins SNAP25 and Ng in AD but not in bvFTD could be due to the topography of brain atrophy they reflect." (PMID 38355535, 2024).
dementia with Lewy bodies (3 papers, 2021 to 2024). "Indeed, most of the data on SNAP-25, β-synuclein, and neurogranin in CSF derive from studies on neurodegenerative disease, such as Alzheimer’s, prion, and Lewy body diseases." (PMID 39708160, 2024).
diffuse large B-cell lymphoma (3 papers, 2016 to 2022). "The expression level of SNAP25 in diffuse large B-cell lymphoma was correlated with patient survival and prognosis." (PMID 35752613, 2022).
Dystonia (3 papers, 2016 to 2023). An abnormally increased muscular tone that causes fixed abnormal postures. "Botulinum toxin type A (BoNT/A) is extensively applied in spasticity and dystonia as it cleaves synaptosome-associated protein 25 (SNAP25) in the presynaptic terminals, thereby inhibiting neurotransmission." (PMID 36782335, 2023). "Botulinum toxin type A inhibits peripheral acetylcholine release by cleaving synaptosomal-associated proteins of 25 kDa (SNAP-25) in the presynaptic membrane of cholinergic nerve terminals, inducing chemical denervation of muscles and relieving symptoms of dystonia." (PMID 27547666, 2016). "Botulinum toxin type A has proteolytic actions on separate cleavage sites in SNAP-25 contribute to inhibiting the release of acetylcholine that result in muscle relaxation, thereby long used in the successful treatments of various dystonias." (PMID 34686203, 2021).
encephalitis (3 papers, 2022 to 2025). An acute inflammatory process affecting the brain parenchyma. "Anti-LGI1 encephalitis patients have elevated neurofilament light chain protein, glial fibrillary acidic protein and chemokine ligand 13 levels and reduced Visinin-like protein 1, Synaptosomal Associated Protein-25 (SNAP-25) and neurogranin levels in the serumand CSF." (PMID 36685530, 2022).
Encephalopathy (3 papers, 2022 to 2024). Encephalopathy is a term that means brain disease, damage, or malfunction. "Overall, SNAP25 encephalopathy caused by single missense point mutations presents with interdependent functional deficits, which must be overcome for successful treatment." (PMID 38411501, 2024).
gastric cancer (3 papers, 2022 to 2024). A primary or metastatic malignant neoplasm involving the stomach. "Recent studies have claimed that neural signaling is of great importance in regulating tumor metabolism and have validated the role of this biological function in regulating SNAP25 expression in gastric cancer metabolism." (PMID 35392903, 2022). "To explore the role of SNAP25 in chemoresistance, we treated SNAP25 knockdown and SNAP25-overexpressing GNEC cell lines with chemotherapeutic agents commonly used in gastric cancer." (PMID 35752613, 2022).
Hyperglycemia (3 papers, 2014 to 2024). An increased concentration of glucose in the blood. "We show that diabetic Goto‐Kakizaki (GK) rats exhibited impaired insulin secretion and hyperglycemia, along with decreased SNAP25 expression and ChREBP phosphorylation in islets." (PMID 39300600, 2024). "Altered expression and localization of SYNTHAXIN-1 and SNAP-25 have been reported in endocrine and neuronal cells exposed to hyperglycaemia." (PMID 24648662, 2014). "It is noteworthy that hyperglycemia inhibits SNAP25 expression in β‐cells." (PMID 39300600, 2024). "We also showed that long-term hyperglycemia led to reduced SNAP-25 and syntaxin-1A expression, which may constitute the major factor for reshaping vesicle fusion dynamics." (PMID 33937248, 2021). "These phenotypes were mostly due to the hyperglycemia-induced reduction in syntaxin-1A (Stx-1A) and SNAP-25 protein, since they could be recapitulated by the knockdown of endogenous Stx-1A and SNAP-25." (PMID 33937248, 2021). "Correspondingly, knocking down syntaxin-1A and SNAP-25 in INS-1 cells decreased the fusion frequency, triggered more kiss-and-run events, and restricted the fusion pore size, which were similar to the effects of hyperglycemia." (PMID 33937248, 2021).
mental disorder (3 papers, 2017 to 2023). A disease that has its basis in the disruption of mental process. "Therefore, the phosphorylation of SNAP-25 would be a promising target for developing novel therapeutics for mental disorders." (PMID 28801590, 2017). "Finally, the mature stage T5 was enriched for synaptic signaling genes (FDR = 5 × 10–16; e.g., CADPS2 and SNAP25) and regulation of membrane potential (FDR = 3 × 10–11; e.g., RIMS1 and SCN2A), and was most specifically marked by RBFOX1, an RNA-binding protein implicated in many mental disorders." (PMID 36865235, 2023). "Although the actual mechanism by which SNAP-25 affects psychiatric disorders are not well known, numerous studies have shown a connection between alterations in SNAP-25 levels and symptoms of multiple mental disorders, including ADHD." (PMID 37629164, 2023).
migraine (3 papers, 2023 to 2025). "Recently, variants in the SNARE genes VAMP2, SNAP25 and STX1A have been studied as potential risk factors in several neurological disorders, including migraine." (PMID 37380951, 2023). "Furthermore, variants in SNAP25 and VAMP2 that affect their expression have been implicated in migraine." (PMID 39924344, 2025).
sarcopenia (3 papers, 2019 to 2025). Progressive decline in muscle mass due to aging which results in decreased functional capacity of muscles. "Thus, our results for the first time show that sarcopenia is associated with SNAP-25 polymorphisms and with a particular profile of miRNAs that regulate SNAP-25 expression." (PMID 34289870, 2021). "For these reasons SNAP-25 was hypothesized to participate to the pathogenic mechanisms involved in sarcopenia." (PMID 34289870, 2021). "The core SNARE synaptosomal-associated protein of 25 kDa (SNAP-25), in particular, could be a key factor in sarcopenia, as it accumulates in the plasma membrane of nerve terminals at NMJ, consistently with its role in regulating exocytosis at peripheral and central synapses." (PMID 34289870, 2021). "Here we analysed the possible association of rs3603050 SNAP-25 polymorphism with sarcopenia, whether miRNAs related with the expression of this gene are differentially expressed in sarcopenic patients, and, finally, the possible effect of rehabilitative treatment on miRNAs expression." (PMID 34289870, 2021). "MiR-451a and miR-421-3p, the two miRNAs that were observed to be differently expressed in sarcopenia, thus regulate two proteins (SNAP-25 and BMP-2) related to muscle function." (PMID 34289870, 2021). "SNARE complex and, in particular, SNAP25 may represent a promising pathway to explore the molecular and cellular mechanisms regulating muscular homeostasis and concur at profiling the sarcopenia biological background." (PMID 31457015, 2019).
tauopathy (3 papers, 2019 to 2022). Neurodegenerative disorders involving deposition of abnormal tau protein isoforms (tau proteins) in neurons and glial cells in the brain. "ADNP showed relatively reduced expression in the ADNP syndrome cerebellum, which was also observed for 25 additional genes (representing >50% of the tested genes), including NLGN1, NLGN2, PAX6, SMARCA4, and SNAP25, converging on nervous system development and tauopathy." (PMID 32661233, 2020). "While this result does not demonstrate a direct role for TIA1 in mediating alternative splicing of Gria2, Snap25, or Camk2b, the results indicate that normalization of splicing represents a clear component of the neuroprotection provided by TIA1 reduction in tauopathy." (PMID 31875547, 2019).
botulism (2 papers, 2017 to 2018). A serious bacterial infection caused by botulinum toxin which is produced by Clostridium botulinum. "Botulinum neurotoxin serotype C (BoNT/C) is a neuroparalytic toxin associated with outbreaks of animal botulism, particularly in birds, and is the only BoNT known to cleave two different SNARE proteins, SNAP-25 and syntaxin." (PMID 28800600, 2017).
breast cancer (2 papers, 2021 to 2025). A primary or metastatic malignant neoplasm involving the breast. "In another study, NUPR1 transcriptionally activated the presynaptic ROS sensor synaptosome associated protein 25 (SNAP25) and maintained the autolysosomal efflux in breast cancer cells." (PMID 34359572, 2021).
congenital myasthenic syndrome (2 papers, 2019 to 2022). Congenital myasthenic syndrome (CMS) is a group of genetic disorders of impaired neuromuscular transmission at the motor endplate characterized by fatigable muscle weakness. "With the exception of the BMP2 gene, only the gene SNAP25 (OMIM#600322), which is related to congenital Myasthenic syndrome 18, has been reported in prenatal diagnosis with decreased fetal movements and in utero onset for possible prenatal clinical diagnosis." (PMID 35227291, 2022).
coronary artery disease (2 papers, 2019 to 2020). "SNAP25 rs36305, Stx-1A rs4717806, and rs2293489, VAMP2 26bp ins/del, Minor allele effect of association with ischemic heart disease (IHD) vs Control group (CG), calculated by regression analysis model with Shesis software." (PMID 31192914, 2019). "SNAP25 rs36305, Stx-1A rs4717806, and rs2293489, VAMP2 26bp ins/del genotypic and allelic polymorphism distribution in patients with ischemic heart disease (IHD) and in the control group (CG)." (PMID 31192914, 2019).
developmental delay (2 papers, 2021 to 2023). "Hemiallelic de novo loss-of-function missense variants of SNAP25 cause CMS with developmental delay and ataxia." (PMID 36835142, 2023).
Huntington disease (2 papers, 2010 to 2013). Huntington disease (HD) is a rare neurodegenerative disorder of the central nervous system characterized by unwanted choreatic movements, behavioral and psychiatric disturbances and dementia. "Furthermore, a loss of SNAP25 was noted in brains of patients suffering from Huntington's disease." (PMID 20305790, 2010).
Insulin resistance (2 papers, 2019 to 2025). Increased resistance towards insulin, that is, diminished effectiveness of insulin in reducing blood glucose levels. "Especially, overexpression or abnormal expression of SNAP-25 has been linked to insulin resistance, as SNAP-25 acts as a physiological brake to impair insulin action, while attenuation or deficiency of SNAP-25 results in higher insulin sensitivity." (PMID 40790236, 2025).
neuroendocrine tumor (2 papers, 2013 to 2024). "Given its significant expression in neuroendocrine tumors, SNAP25 has been the focus of extensive research." (PMID 39430761, 2024). "Abnormal SNAP25 expression or function is linked to neurological disorders (like Alzheimer’s and ADHD) and the development and progression of various neuroendocrine tumors." (PMID 39430761, 2024). "EGF and CNTF direct fusions were as active on the neuroendocrine tumor cells as the stapled products in terms of selectivity and cleavage of SNAP25." (PMID 23638840, 2013).
Paralysis (2 papers, 2019 to 2025). Paralysis of voluntary muscles means loss of contraction due to interruption of one or more motor pathways from the brain to the muscle fibers. "It is one of the strongest known neurotoxins and can block the release of acetylcholine by cleaving SNAP-25, thereby blocking nerve signaling and causing muscle paralysis." (PMID 40864052, 2025). "The light chain of BoNT-A cleaves apart synaptosome-associated protein 25 in presynaptic neurons, thereby inhibiting the release of the acetylcholine neurotransmitter by disrupting vesicular fusion with the neuronal cell membrane, resulting in flaccid muscle paralysis." (PMID 31689912, 2019).
pheochromocytoma (2 papers, 2017 to 2019). "It was also clarified that the phosphorylation of SNAP-25 at Thr138 inhibits noradrenaline secretion of differentiated PC12 pheochromocytoma cells." (PMID 28486561, 2017). "For example, data derived from microarrays and proteomics have shown reduced expression of various components of the regulated secretory pathway (e.g., SNAP25, syntaxin, rabphilin 3A, annexin) in VHL-related pheochromocytomas compared to RET-related pheochromocytomas." (PMID 31390824, 2019).
prion disease (2 papers, 2022 to 2023). A transmissible disease that is caused by a protein that is able to induce abnormal folding of normal cellular proteins, leading to characteristic spongiform brain changes, which are associated with neuronal loss without an inflammatory response. "When considering the whole CJD cohort, CSF SNAP-25 was significantly associated with survival (HR 1.71 [1.48–1.99], P < 0.001), even after accounting for covariates known as prognostic factors in prion disease as codon 129 genotype, age at LP and time from onset to LP." (PMID 37684653, 2023). "Synaptic proteins, including SNAP-25 and syntaxin 1A/1B, as well as signaling proteins, including calcium–calmodulin protein kinase 4 and mitogen-activated protein kinases (such as MAPK8), showed decreased expression in prion disease." (PMID 36378750, 2022).
proteinopathies (2 papers, 2022 to 2025). "This feature of SNAP25 is similar to the amyloid-β and α-synuclein protein structures, which are associated with proteopathies, AD, and Parkinson’s disease." (PMID 36430976, 2022). "Thus, SNAP25 can probably be considered as a link between synaptopathies and proteopathies." (PMID 36430976, 2022).
small cell lung carcinoma (2 papers, 2022 to 2024). Small cell lung cancer (SCLC) is a highly aggressive malignant neoplasm, accounting for 10-15% of lung cancer cases, characterized byrapid growth, and early metastasis. "In this analysis, we observed a significant upregulation of SNAP25 in small cell lung cancer compared to normal lung tissue." (PMID 39430761, 2024). "Further analysis of other types of NEC as well as small cell lung cancer, which resembles NEC on a molecular level, has identified RUNDC3A as an upstream molecule that regulates SNAP25 expression and the associated phenotypes that could enhance chemoresistance in NECs." (PMID 35752613, 2022).
Stroke (2 papers, 2016 to 2024). Sudden impairment of blood flow to a part of the brain due to occlusion or rupture of an artery to the brain. "In our analysis, we found SNAP25 significantly reduced in isolated synaptosomes at 24 h after stroke." (PMID 38769196, 2024). "Upregulation of SNAP25 was found to be a synaptic response to ischemic damage in the hippocampus of gerbils two days after stroke, while others have found a prominent decrease of SNAP25 and synaptophysin for the same time point in the stroked gerbils that were subsequently incremented at 14 days." (PMID 38769196, 2024). "Thus, in a gerbil model of stroke, the number of synapses initially decreased up to day 4, then started recovering one week after stroke, and increased SNAP-25 (a synaptic marker protein involved in axonal outgrowth) immunoreactivity was observed as early as two days after ischemic induction." (PMID 38769196, 2024). "Notably, expression levels of the synaptic markers SNAP25 and PSD95 at 24 h post-stroke were significantly lower in the tMCAO group, possibly indicating a substantial loss of synapses at this time point (both p = 0.0286)." (PMID 38769196, 2024).
tetanus (2 papers, 2017 to 2023). A serious infectious disorder that follows wound contamination by the Gram-positive bacterium Clostridium tetani. "We searched in this database for the presence of mutations at the sites of tetanus (TeNT) and botulinum neurotoxins (BoNTs) cleavages of the three SNARE proteins: VAMP, SNAP-25 and Syntaxin." (PMID 29257047, 2017).
type 1 diabetes (2 papers, 2012 to 2017). "Western blot analysis showed a reduction of the immunoreactivity of synaptophysin (−23.3±4.9%, n = 6, P<0.05) and SNAP25 (−28.6±6.5%, n = 6, P<0.05) in hippocampal membranes, indicating the occurrence of synaptic degeneration, previously reported to occur in models of type 1 diabetes." (PMID 22514596, 2012).
adenovirus infection (1 paper, 2021). "miR-27 can affect adenovirus infection by targeting the 3′UTR region of SNAP25 and TXN2." (PMID 34360898, 2021).